ARID1A (AT-rich interaction domain 1A)
Diseases named in the same sentence as ARID1A in open-access papers (continued):
Sharing a sentence is not in itself a finding about the gene and the disease.
breast carcinoma (continued). "Compared with the somatic mutation profile of general breast cancers reported in the TCGA dataset, breast cancers from MMR variant carriers might have more PTEN mutations [20.0% (2/10) vs. 3.6% (35/982), P = 0.006] and ARID1A mutations [20.0% (2/10) vs. 3.0% (29/982), P = 0.002]." (PMID 35449176, 2022). "Hence, it is plausible that inactive ARID1A mutants are found in endocrine-resistant breast cancer." (PMID 34804958, 2021). "It suggested that ARID1A gene may involve in carcinogenesis in some subtypes of breast cancer." (PMID 26904685, 2016). "We identified 49 genes (10.6%) concurrently upregulated and 168 genes (20.1%) concurrently downregulated in ARID1A‐mutant and ARID1B‐high breast cancer samples." (PMID 40671262, 2025). "Other interesting observations included the mutual exclusivity of KEAP1 and STK11 in NSCLC and enrichment for CDH1, PIK3CA, and ARID1A along with mutual exclusivity with BRCA1/2, PTEN, and ESR1 in breast cancer." (PMID 40178042, 2025). "This study aims to understand the context-dependent role of ARID1A, a key component of the SWI/SNF chromatin remodeling complex that shows frequent alterations across cancers, including breast cancer." (PMID 41514650, 2025). "For the non-cancer adipose-breast network that we applied to the breast cancer GWAS, Downstreamer prioritised seven known breast cancer driver genes among the top 100 genes: CREBBP, TRPS1, ARID1A, ARID1B, XBP1, SPEN and NUMA1." (PMID 39010058, 2024). "Inhibiting these synthetic lethality targets results in selective vulnerabilities in ARID1A mutant OCCC, CRC, and breast cancer cells." (PMID 38811536, 2024). "To deepen our understanding of the role of ARID1A in TNBC, we collected specimens from breast cancer patients and investigated its impact on the prognosis of TNBC patients." (PMID 37173914, 2023). "In Takao’s study, they found that the downregulation of ARID1A increases RAB11FIP1 expression, resulting in accumulation of integrin α5β1 on breast cancer cell membrane, thus enhancing cancer cell invasion." (PMID 36890819, 2023). "ARID1A and SMARCB1 inactivation have recently been shown to reduce the sensitivity of breast cancer cells to estrogen receptor inhibition, giving support to our findings in a second cancer type." (PMID 37554444, 2023). "Meanwhile, eMDSCs significantly downregulate ARID1A expression and promote EMT in luminal A breast cancer." (PMID 36329699, 2022). "Furthermore, Kaplan-Meier analysis in 140 primary breast cancer tissues from cohort 1 demonstrated that patients with lower ARID1A expression showed a worse outcome, which was reconfirmed by online Kaplan–Meier-Plotter database-analyzed overall survival plot of breast cancer." (PMID 36329699, 2022). "The low mRNA expression of ARID1A is related to shorter overall survival in luminal A and human epidermal growth factor receptor 2 (HER2)-rich breast cancer." (PMID 34804958, 2021). "Western blotting of PARP1 co-immunoprecipitated proteins confirmed the direct interaction of PARP1 with ARID1A and BRG1, but also with other subunits of SWI/SNF, such as SMARCC1 and SMARCC2, in the studied breast cancer cell lines." (PMID 31614656, 2019). "ARID1A down‐regulation predicts a significantly shorter RFS and poorer response to paclitaxel‐based chemotherapy in breast cancer." (PMID 29392887, 2018). "Upon ARID1A knockdown, MCF7 breast cancer cells and primary MRC5 cells exhibited a significantly increased sensitivity towards the AKT-inhibitors MK-2206 and perifosine, as well as the PI3K-inhibitor buparlisib." (PMID 24979463, 2014). "Like breast cancer, NPC has multiple recurrent aberrations in ARID1A genes." (PMID 39885374, 2025).
breast carcinoma (continued). "IHC analysis of ARID1A levels in breast cancer samples showed a negative correlation between ARID1B and ARID1A." (PMID 40671262, 2025). "The low levels of ARID1A observed in breast cancer may be attributed to ARID1B higher affinity for the BAF core, increased ARID1A degradation, or both." (PMID 40671262, 2025). "ARID1A and ARID1B may influence breast cancer by promoting various cellular functions related to tumor suppression, hence controlling aggressiveness and therapeutic response." (PMID 41278204, 2025). "Similarly, hyperactivated ARID1A, phospho-HDAC6 and FOXM1 in Ewing’s sarcoma and breast cancer remodel chromatin structure via phase separation, driving oncogenic transcription and tumor progression." (PMID 40507965, 2025). "Moreover, among the tested ER+ breast cancer cells, ARID1A mutant T47D cells had higher ARID1B mRNA and protein levels compared to those of ARID1A WT cells." (PMID 40671262, 2025). "Although ARID1A is not a core subunit of the SWI/SNF complex, it is the most common SWI/SNF mutation component in breast cancer." (PMID 38365747, 2024). "We found that eMDSCs was negatively correlated with the expression of ARID1A protein and accelerated EMT progression in luminal A breast cancer patients, which suggest a possibility that eMDSCs promote breast cancer cell migration and invasion through down-regulation of ARID1A." (PMID 36329699, 2022). "While the interrelation between GR and SMARCE1 and ARID1A in breast cancer has not been clearly evaluated yet, both SWI/SNF subunits were associated with breast cancer metastasis and breast cancer patient survival." (PMID 35761157, 2022). "Moreover, the reduced function of ARID1A and activated signaling of PI3K/AKT have been shown in endocrine resistance among patients with breast cancer." (PMID 35764927, 2022). "The expression levels of METTL8 in most breast cancers are upregulated, mediated by the transcription factor Yin Yang 1 (YY1), which in turn modify AT-rich interactive domain-containing protein 1 A (ARID1A) to promote tumor growth and the migration of cancer cells." (PMID 34862464, 2021). "Low mRNA expression of ARID1A (p=0.0096), ARID2 (p=0.0066), ARID3B (p= 0.000024), ARID5A (p=0.0435), ARID5B (p=0.0022), JARID1A (p=0.0044), JARID2 (p=0.0463) were interrelated with worse OS in grade III breast cancer patients." (PMID 33592583, 2021). "ARID1A, a member of the switching defective/sucrose non-fermenting complexes, is generally considered a tumor suppressor gene in breast cancer, hepatocellular carcinoma and pancreatic cancer." (PMID 30849962, 2019). "Previous investigations had reported that TSC2, ARID1A, AXIN1, CASP8, CDH1, and ASXL1 could play roles in tumor suppression in diverse cancer types, including breast cancer." (PMID 29414922, 2018). "Targeting ARID1A phosphorylation pathways, potentially via MAPK inhibitors or BRD4/BRD9 antagonists, could restore its suppressive activity and improve treatment outcomes in breast cancer." (PMID 41572083, 2026). "Although there was no mRNA expression difference of ARID1A in breast cancer and normal tissues, the mRNA expression of ARID1A in no-luminal subtypes were lower than those in luminal subtypes of breast cancer tissues, and the prognostic significance of this gene was prominent in the present study." (PMID 33592583, 2021).
breast carcinoma (continued). "Because the protein expression of ARID1A was limited in 20% cases of breast cancer, we think that ARID1A may be not master gene in carcinogenesis of breast cancer." (PMID 26904685, 2016). "There were 60 (80%) cases of breast cancers with negative expression of ARID1A." (PMID 26904685, 2016). "Positive correlations between ARID1A and PGR expression, and negative correlations between EZH2 and PGR/ESR1 expression, were also observed in breast cancer patient samples." (PMID 35326450, 2022). "Although it still has some limitations such as not directly showing the mRNA methylation of ARID1A and modulation of PI3K-AKT pathway via METTL8, this study can be an important clue to better understand the epigenetic regulation of breast cancer." (PMID 34063990, 2021). "The expression of ARID1A, ARID1B, ARID2, ARID3A, ARID4A, and ARID4B in no-luminal subtypes was lower than luminal subtypes, however, ARID3C, ARID5A, and JARID2 mRNA expression were higher in no-luminal subtypes of breast cancer tissues." (PMID 33592583, 2021).
colorectal cancer (90 papers, 2015 to 2026). A primary or metastatic malignant neoplasm that affects the colon or rectum. "ARID1A mutation is frequently observed in cancers and is known to be associated with tumor activity and poor prognosis, such as colorectal cancer." (PMID 40750787, 2025). "The ARID1A gene is mutated in a wide range of cancer types, including up to 50% of ovarian clear cell cancers (OCCCs) and around 10% of colorectal cancers." (PMID 40938753, 2025). "In this study, we report that ARID1A-deficient colorectal cancer (CRC) cells induce synthetic lethality when treated with inhibitors of c-MET receptor tyrosine kinase." (PMID 40369167, 2025). "This was apparent in ovarian and colorectal cancer cell line models, and in vivo studies suggest that G4 ligands hold promise for ARID1A-deficient cancers." (PMID 40938753, 2025). "In colorectal cancer, truncating mutations in ARID1A or PBRM1 have been linked to increased TMB, robust cytolytic immune infiltration, and durable responses to ICIs." (PMID 41438758, 2025). "In colorectal cancer, ARID1A‐mutated tumours exhibited increased tumour mutational burden, frameshift mutations and higher expression of immune checkpoint genes." (PMID 40621620, 2025). "AURKA inhibition or depletion is synthetically lethal in ARID1A-deficient colorectal cancer (CRC) cells as well." (PMID 39334449, 2024). "In colorectal cancer, loss of ARID1A leads to a decrease in p21 expression, which is further supported in gynecologic cancers." (PMID 38811536, 2024). "Colorectal Cancer: ARID1A mutations are detected in 10% of colorectal cancers and are strictly related to mismatch repair deficiency." (PMID 38893181, 2024). "To date, the association between ARID1A and immune-related molecules has been investigated only in relation to colorectal cancer, targeting MSS cases." (PMID 38893118, 2024). "It has now been shown that in endometrial and colorectal cancers, ARID1A deficiency is associated with MLH1 silencing due to promoter hypermethylation." (PMID 39697230, 2024). "ARID1A-deficient expression in colorectal carcinoma is frequently associated with MMR protein deficiency and BRAF mutation and exhibits medullary differentiation and mucinous differentiation." (PMID 38217014, 2024). "ATR inhibitors are synthetically lethal in ARID1A-deficient human colorectal cancer and OCCC cell lines and xenograft models." (PMID 38275587, 2023). "Aurora-A inhibitor I induces G2/M cell cycle arrest, multinucleation, and apoptosis in ARID1A-deficient colorectal cancer cells." (PMID 35054947, 2022). "A study in colorectal cancer cells showed that inactivation of ARID1B in ARID1A-mutated cells increases their sensitivity to IR, though only modestly." (PMID 36605718, 2022). "Upregulation of tumor suppressor gene ARID1A in CRC cell lines by HDACs pharmaceutical inhibitors seems to be a therapeutic approach for the treatment of ARID1A-deficient colorectal cancer." (PMID 35611248, 2022). "In this work, we show data to support ARID1A mutations confer resistance to cetuximab treatment in colorectal cancer." (PMID 36117191, 2022). "Loss of ARID1A, a tumor suppressor gene, is associated with the higher grade of colorectal cancer (CRC)." (PMID 35069887, 2022). "ARID1A mutations are frequently observed in colorectal cancers (CRCs) and have been reported to be associated with high mutational burden and tumor PD‐L1 expression in vitro." (PMID 34042312, 2022).
colorectal cancer (continued). "In colorectal cancer patients, mutations in ARID1A are associated with higher MSI, TMB, and cytotoxic T cell infiltration, which result in improved prognosis." (PMID 35707003, 2022). "Using a panel of colorectal cancer cells that express ARID1A vs. a panel of ARID1A-deficient cells, the authors showed that downregulation of ARID1B using siRNA increased the sensitivity to IR in cells lacking both subunits." (PMID 36605718, 2022). "A recently published study revealed that targeting Aurora kinase A induced synthetic lethality in ARID1A deficient colorectal cancer cells." (PMID 36269546, 2022). "Knocking down ARID1B in ARID1A-deficient colorectal cancer cells sensitized the cells to DNA damage caused by irradiation." (PMID 34737943, 2021). "It has been elucidated that the chromatin accessibility alters followed by phenotypic abnormality once the deficient expression of SWI/SNF components occurs, e.g., ARID1A in HCT116 colorectal cancer cells and injury-induced liver-progenitor-like cells." (PMID 34689165, 2021). "A recent publication also suggested Aurora A as a potential therapeutic target in ARID1A-deficient colorectal cancer cells." (PMID 33941852, 2021). "ARID1A mutations are present in 10% of colorectal cancers and, similar to GC, are thought to be caused by mismatch defects." (PMID 34671561, 2021). "On the other hand, ARID1A has a synthetic lethal interaction with AURKA in colorectal cancer cells such that AURKA inhibition can selectively impede the growth of ARID1A-deficient colorectal cancer cells." (PMID 34737943, 2021). "It is reported that depletion of ARID1B sensitizes colorectal cancer cells with ARID1A mutation to ionizing radiation." (PMID 34434896, 2021). "Here, we investigated weather knockdown of ARID1B, one of two mutually exclusive subunits within the SWI/SNF complex, can sensitize colorectal cancer cell lines mutated in the other subunit, ARID1A, to ionizing radiation (IR)." (PMID 31796878, 2019). "In this study, we sought to examine the transcriptional mechanisms underlying the tumor suppressor function of ARID1A in colorectal cancer." (PMID 31217031, 2019). "ARID1A-mutated colorectal cancer (CRC) cell lines are selectively sensitized to IR after siRNA mediated ARID1B depletion, as measured by clonogenic survival." (PMID 31796878, 2019). "Mutations in ARID1A that lead to inactivation or loss of expression are frequent and widespread across many cancer types including colorectal cancer (CRC)." (PMID 31217031, 2019). "Using a Cox P‐value of <.05, lower ARID1A expression in blood, breast, lung and colorectal cancers, with the exception of soft tissue cancer, was associated with a poorer outcome." (PMID 29392887, 2018). "Mutations in ARID1A have recently been identified in diverse cancer types, including ovarian, endometrial, and colorectal cancer." (PMID 28967863, 2017). "Inactivating ARID1A mutations have been detected across a range of diverse cancer types, including 9.4% of colorectal carcinomas and up to 60% of OCCCs." (PMID 28967863, 2017). "Although the effects of ARID1B knockdown are limited in comparison, our findings show that the ability of ARID1B to regulate accessibility underpins its absolute requirement for proliferation of ARID1A-deficient colorectal carcinoma cells and mutant OCCCs." (PMID 28967863, 2017). "A recent study by Mathur and colleagues characterized SWI/SNF genomic occupancy in HCT116 colorectal carcinoma cells with wild-type ARID1A or homozygous truncating ARID1A mutations." (PMID 28967863, 2017). "We employed isogenic HCT116 colorectal carcinoma cells that are wild-type for ARID1A (WT) or engineered for homozygous ARID1A protein loss (ARID1A-/-) by introduction of an early stop codon (Q456*) by gene trap (Horizon Discovery)." (PMID 28967863, 2017). "Thus, microsatellite stable colorectal cancer patients with ARID1A mutation are more responsive to immunotherapy." (PMID 40621620, 2025).